IL33 (interleukin 33)
Diseases named in the same sentence as IL33 in open-access papers (continued):
Sharing a sentence is not in itself a finding about the gene and the disease.
depression (continued). "In addition, the expression of IL1RL1 (also known as ST2 and IL33R), has been shown to be negatively associated with depression severity in post-stroke depression, whereas the expression of its ligand, the cytokine IL33, was positively associated with severity." (PMID 37186582, 2023). "Clinical studies show decreased IL-33 levels in the blood and cerebrospinal fluid of depression patients, correlating with disease severity." (PMID 41760068, 2026). "This review explores the dual roles of interleukin-33 (IL-33) in neuroimmune regulation, neuroinflammation, and neuroplasticity, aiming to investigate its potential as a therapeutic target for depression." (PMID 41760068, 2026). "In a fully adjusted model, depression was significantly associated with higher levels of IFN-γ and IL-1ra; IL-33, CCL-2, CCL-4 and TNF- α remained significant below the Bonferroni threshold." (PMID 39922907, 2025). "In this study, we employed IL-33-overexpressing mice to detect and observe circadian rhythmic behavioral changes through anxiety- and depression-like behaviors, combined with transcriptomics large-scale analysis." (PMID 40076523, 2025). "In this study, we performed transcriptomic analysis of the hippocampus of IL-33-overexpressing mice to provide new ideas to explore the pathogenesis of inflammation-mediated depression at the transcriptional level." (PMID 40076523, 2025). "Women with a history of recurrent major depressive disorder (rMDD) were found to have higher serum IL-33 levels in a more comprehensive cross-species study of humans and rats." (PMID 40076523, 2025). "The current study proposes that lower IL-33 and higher MANF serum levels are associated with MDD progression and depression severity." (PMID 38216957, 2024). "Although there is inconsistent research on IL-33’s effects on depression, research points to a protective effect." (PMID 39273641, 2024). "Due to its magnitude and unclear cytokine balance with serum, IL-33 in cerebrospinal fluid presents difficulties that make it challenging to consistently determine its impact on depression." (PMID 39273641, 2024). "Serum IL-33 has a clear correlation to depression among female patients who have experienced abuse as children in the past, alopecia areata, systemic lupus erythematosus, and recurrent major depressive disorder." (PMID 39273641, 2024). "The HPA axis, neuroinflammation, and monoamine signaling were supported by IL-33 participation in an experimental study on male mice that found that persistent stress produced anxiety or depression-like behavior." (PMID 39273641, 2024). "While direct research on chronic stress and depression is scarce, a theoretical theory proposes an indirect link between IL-33, human microglia, and depression triggers, which influences neurodevelopment and synapse count." (PMID 39273641, 2024). "Earlier research reveals that IL-33 has a dual role as a pro-inflammatory factor influencing depression development and a neurotrophic factor controlling depression development." (PMID 39273641, 2024). "By controlling the development of the central nervous system, microglial cells produce IL-33 in the brain, which affects memory and emotion-related areas, synaptic remodeling, and depression." (PMID 39273641, 2024). "IL-33 has a critical role in brain areas important for emotional function, implying its importance in depression development." (PMID 39273641, 2024). "Depression is a result of neurodevelopmental degenerative alterations, and IL-33 influences synaptic quantity and remodeling by functioning as a neurotrophic factor and a pro-inflammatory factor." (PMID 39273641, 2024). "In terms of its function in depression, IL-33 mRNA levels are greatest in the brain and spinal cord, particularly in stress-responsive areas such as the paraventricular nucleus and prefrontal cortex." (PMID 39273641, 2024).
depression (continued). "Using Beck’s depression inventory, we observed an increase in plasma IL-17A and IL-33 in women with T. gondii infeCction diagnosed with mild DS, whereas neuroserpin was associated with minor and moderate/severe DS." (PMID 38835777, 2024). "Despite numerous studies on IL-33 and depression, encompassing variations in circulating levels throughout the illness and electroconvulsive treatment, the findings are conflicting." (PMID 39273641, 2024). "Both IL-33 and IL-17A have been identified as potential prognostic markers in human toxoplasmosis and depressive disorders, as evidenced by their high plasma levels in pregnant women with T. gondii infection having mild DS." (PMID 38835777, 2024). "The Beck Depression Inventory Questionnaire data revealed that plasma concentrations of IL-33 and IL-17A were higher in T. gondii-infected pregnant women diagnosed with mild DS." (PMID 38835777, 2024). "In patients with bipolar illness, major depressive disorder during pregnancy, postpartum depression, and Alzheimer’s disease, there are elevated levels of IL-33 in the cerebrospinal fluid." (PMID 39273641, 2024). "Subgroup analysis results showed that IL-33 and ST2 levels in cerebrospinal fluid and serum is positive correlated with reduced risk of major depressive disorder (MDD) and bipolar disorder (BD)." (PMID 38025419, 2023). "IL-33 levels were reported to increase with the severity of depression symptoms, as assessed with the Hamilton Depression Scale (HAM-D)." (PMID 33810498, 2021). "In the RT alone group, the peak change in cytokine levels (depression or elevation) was seen at 4 weeks during treatment for IL-33, IP-10, MCP-1, & MIP-1α." (PMID 25289758, 2014). "Animal model studies and clinical evidence regarding IL-33 levels in depression were also analyzed." (PMID 41760068, 2026). "The effect of IL-33 on mitochondrial circadian rhythms may be an important mechanism in the development of depression." (PMID 40076523, 2025). "This suggests that IL-33 may not only serve as a marker of neuroinflammation but may also play a direct role in the behavioral manifestations of depression." (PMID 40305200, 2025). "The IL-33-overexpressing mice showed some anxiety- and depression-like behaviors." (PMID 40076523, 2025). "Studies have shown that IL-33 may influence depression-related behavioral traits, with knockout models exhibiting impaired social recognition and anxiety-like behaviors." (PMID 40305200, 2025). "Additionally, the ST2 receptor, which mediates IL-33 signaling, is downregulated in the prefrontal cortex of MDD patients, implicating the IL-33/ST2 axis as a potential biomarker for inflammatory-driven depression." (PMID 40244068, 2025). "Changes in transcriptional rhythms in IL-33-overexpressing mice may explain depression-like behaviors in IL-33-overexpressing mice." (PMID 40076523, 2025). "The underlying mechanism may be related to the regulation of mitochondrial metabolism and mitochondrial dynamics by IL-33, which provides novel insights into the pathogenesis of depression." (PMID 40076523, 2025). "Moreover, the severity of depression would be measured by the altered IL-33 and MANF levels, if any." (PMID 38216957, 2024). "The effects of IL-33 on depression among animals have been confirmed." (PMID 39273641, 2024). "Few previous studies have tried to conclude the involvement of IL-33 in depression." (PMID 38216957, 2024). "Subgroup studies demonstrate the preventive function of IL-33 against depression, independent of the cause or course of therapy." (PMID 39273641, 2024). "Despite its high concentration, serum IL-33 exhibits correlations with depression, which may be explained by active transport and blood–brain barrier leakage." (PMID 39273641, 2024).
depression (continued). "The interaction between cytokines, like IL-33, and pathways, like the kynurenine pathway, has revealed new treatment targets in mood disorders, including major depressive disorder and bipolar disorder, and it has also shed light on the intricate role that neuroinflammation plays in mental health." (PMID 39273641, 2024). "In PTSD comorbid with depression, IL-33 levels were higher than in depression alone." (PMID 33810498, 2021). "Future research could be focused on the analysis of IL-33 and other inflammatory cytokines in relation to depression symptoms in the postmenopausal period, with particular attention given to the nutritional state of the women considered." (PMID 33810498, 2021). "IL-33 holds promise as a potential biomarker for depression and may serve as a therapeutic target." (PMID 41760068, 2026). "Upon inflammatory stimulation, cells produce IL-33, which activates downstream pathways that regulate pro-inflammatory and Th2-related cytokines, making it an important participant in the cytokine hypothesis of depression." (PMID 39273641, 2024). "What IL-28A and IL-33 have in common (more specifically, lower concentrations of IL-28A and high concentrations of IL-33) is their expression in neuroinflammatory processes, depression, with and without PTSD, risk of depression as well as in insomnia comorbid with depression." (PMID 37759873, 2023). "The alarmin IL-33, IL-17A, and the chemokine CCL2 have been highlighted in studies of depressive disorders, and their high production/expression was demonstrated in chronic T. gondii research in both experimental models and humans." (PMID 38835777, 2024). "We recommend more investigation, including a significant population, to determine the precise function of IL-33 and MANF in depression." (PMID 38216957, 2024). "Another study found that treatment of major depression by transcranial direct current stimulation resulted in no significant change in plasma IL-33 levels before and after treatment." (PMID 40076523, 2025). "IL-33 and IL-31 were significantly higher in patients with AA than in HCs; there were no significative relationship between depression or anxiety with IL-31 or IL-33." (PMID 33810498, 2021). "Hence, it is hypothesized that IL-33 or ST2L abnormality affects behavioral trait in same behavioral categories: social behavior and depression-like behavior." (PMID 32393354, 2020). "When compared with participants without depression or subsequent cognitive decline, patients with LLD were shown to have elevated concentrations of CCL-2 and CCL-4 and cytokines IL-17a, IL-33, IFN-γ and IL-1ra, as well as IL-33 in most models." (PMID 39922907, 2025).
osteoporosis (19 papers, 2016 to 2025). A condition of reduced bone mass, with decreased cortical thickness and a decrease in the number and size of the trabeculae of cancellous bone (but normal chemical composition), resulting in increased fracture incidence. "Recent research has shown that postmenopausal women who have estrogen deficiency with osteoporosis have low blood levels of IL-33." (PMID 39200100, 2024). "Interleukin-33 (IL-33) and interleukin-31 (IL-31) are two cytokines that have been implicated in the pathogenesis of several bone-related disorders, including osteoporosis." (PMID 39767728, 2024). "FOXP3, a transcription factor for Treg cells, was elevated after IL-33 treatment, which was otherwise low in the D-gal–administered group and Tregs have been shown to reduce bone loss and osteoporosis." (PMID 39224568, 2024). "The resorptive function was validated also by the result of one study in which sST2 significantly correlated with higher cortical porosity and cortical pore volume in PSA patients, underlying IL33/ST2 axis is linked with osteoporosis in PSA." (PMID 31736655, 2019). "Release of alarmins or DAMPs (danger-associated molecular patterns), including IL-33, from damaged cells is a relevant mechanism by which immune cells can be alerted of tissue damage, and alarmins play a key role in the development of acute or chronic inflammatory diseases, cancer and osteoporosis." (PMID 32069819, 2020). "The deepening of the knowledge of the roles of IL-31 and IL-33 in the immunoskeletal interface can contribute to better understanding of those mechanisms underlying the functioning of the immune system that trigger osteoclastogenic inflammatory reactions, crucial in osteoporosis." (PMID 32069819, 2020). "The authors first evaluated patients with sarcopenia, osteoporosis, or osteosarcopenia, and found significantly decreased levels of IL-33 in skeletal muscle, bone matrix, proximal bone marrow, and serum of osteosarcopenia patients." (PMID 41365059, 2025). "Mendelian Randomization analysis of patient data led to the identification of a cause-effect relationship between low muscle strength and low IL-33 levels, and between high IL-33 levels and low incidence of osteoporosis." (PMID 41365059, 2025). "Studies in postmenopausal women revealed significantly elevated serum IL-31 levels (43.12 ± 6.97 pg/mL vs. 29.58 ± 6.09 pg/mL in healthy controls) and significantly reduced IL-33 levels (3.53 ± 2.45 pg/mL vs. 13.72 ± 5.39 pg/mL) in osteoporosis patients." (PMID 41368642, 2025). "Th2 cytokines such as IL-31 and IL-33 also regulate bone metabolism and can influence the progression of osteoporosis." (PMID 39200293, 2024). "Following clinical studies have been conducted to better understand the role of IL-33 in osteoporosis." (PMID 39200293, 2024). "IL-33 has anti-osteoclastic properties, leading to the potential use of recombinant IL-33 in the treatment of osteoporosis." (PMID 39200100, 2024). "Previous studies have indicated that IL-33 inhibits osteoclastogenesis, suggesting a potential role in mitigating osteoporosis." (PMID 39224568, 2024). "In conclusion, the role of IL-33 in bone metabolism is considered a significant factor in the pathogenesis of osteoporosis." (PMID 39200293, 2024). "It has been observed that postmenopausal women with osteoporosis have lower levels of IL-33 compared to healthy control women." (PMID 39200293, 2024). "IL-33 is receiving increasing attention as a cytokine that regulates bone metabolism and is involved in the pathogenesis of osteoporosis." (PMID 39200293, 2024). "These potential effects of IL-33 in maintaining bone health represent a promising area for the treatment of osteoporosis and other bone diseases." (PMID 39200293, 2024). "It appears from clinical and experimental data that the IL-33/IL-31 axis plays a significant part in osteoporosis." (PMID 39224568, 2024).
osteoporosis (continued). "Recent evidence suggests that the IL-33/IL-31 axis constitutes a link between accelerated atherosclerosis and osteoporosis in psoriatic arthritis (PsA)." (PMID 32069819, 2020). "Findings from IL-33−/− and ST2−/− mouse models of postmenopausal osteoporosis revealed that IL-33 and its receptor protects the maxilla and femur from bone loss during physiological bone remodeling." (PMID 32069819, 2020). "Clinical and experimental observations suggest an important role of the IL-33/IL-31 axis in osteoporosis." (PMID 32069819, 2020). "Among these a significative role is played by IL-31 and IL-33, whose role has recently been investigated also in osteoporosis." (PMID 31973226, 2020). "In general, it can therefore be suggested that IL-31 is osteoclastogenic, while IL-33 is protective, in the context of osteoporosis." (PMID 32069819, 2020). "Recently evidence has emerged of the role of two new cytokines of the Th2 profile, IL-31 and IL-33, in bone remodeling and osteoporosis." (PMID 32069819, 2020). "In this review, we performed a literature review of the current evidence on the RAGE signaling pathway and the roles of HMGB, S100, IL-1, and IL-33 alarmins in bone turnover and osteoporosis." (PMID 32204562, 2020). "Here we focus on two newly discovered Th2 cytokines, IL-31 and IL-33, whose implications in osteoporosis are recently emerging." (PMID 32069819, 2020). "Overall, our studies have shown that IL-33 is decreased in osteoporosis, whereas IL-31 is increased." (PMID 32069819, 2020). "In view of the crucial role of this cytokine in inflammation and bone remodeling, we measured IL-33 levels in the serum of postmenopausal women with osteoporosis." (PMID 30846811, 2019). "Although it seems confirmed a role of IL-33 in the pathogenesis of many inflammatory diseases, the same cannot be said for osteoporosis, where IL-33 action is still debated." (PMID 30846811, 2019). "The authors proposed that reduction of IL-33 in sarcopenia might lead to development of osteoporosis, and hence osteosarcopenia." (PMID 41365059, 2025). "Thus, although the background reports indicate a role for IL-33 in the pathogenesis of osteoporosis, the effect of IL-33 exogenous administration on skeletal health has never been explored in an aging osteoporotic animal model." (PMID 39224568, 2024). "Based on our studies, we propose that IL-33 may be an effective therapy in treating aging-induced dementia and osteoporosis." (PMID 39224568, 2024). "The cytokines IL31 and IL33 are reported to play a role in bone remodeling and osteoporosis." (PMID 39767728, 2024). "On the other hand, IL-33 has been shown to enhance bone formation and prevent bone loss by modulating the expression of IL31, suggesting that it has a protective effect against osteoporosis in animal studies." (PMID 39767728, 2024). "In addition, the IL-33/IL-31 axis is known to play a significant role in the development of osteoporosis." (PMID 39767728, 2024). "Additionally, IL-33 prevents osteoporosis by increasing apoptosis in osteoclasts and directly affecting osteoblasts." (PMID 39200293, 2024). "IL-31 and IL-33 are two cytokines of the Th2 cytokine lineage which play a role in osteoporosis." (PMID 35707276, 2022). "Among the interleukins involved in osteoporosis, interleukin 33 (IL-33) is considered an alarmin." (PMID 32204562, 2020). "Therefore, the dual-function alarmin IL-33 can either exert beneficial skeletal effects, leading to bone tissue repair, or provoke deleterious inflammation, leading to osteoporosis." (PMID 32069819, 2020). "Even the extracellular release of IL-33 by damaged cells during inflammatory stress can be either deleterious, such as in the context of allergic inflammation, or protective and repairing as in the case of osteoporosis." (PMID 32069819, 2020). "Given osteoporosis is characterized by a Th1 immune response, the IL-33/ST2 axis could exert protective effects by inducing a switch from Th1 to Th2 immune responses." (PMID 32069819, 2020).